SCRIB (scribble planar cell polarity protein)
Diseases named in the same sentence as SCRIB in open-access papers (continued):
Sharing a sentence is not in itself a finding about the gene and the disease.
lung adenocarcinoma (1 paper, 2021). A carcinoma that arises from the lung and is characterized by the presence of malignant glandular epithelial cells. "For example, SCRIBe, the eRNA associated with oncogene SCRIB, was found to be differentially expressed among lung adenocarcinoma patients according to smoking history." (PMID 34900441, 2021).
myeloproliferative neoplasm (1 paper, 2016). A clonal hematopoietic stem cell disorder, characterized by proliferation in the bone marrow of one or more of the myeloid (i.e., granulocytic, erythroid, megakaryocytic, and mast cell) lineages. "SCRIB has been reported in myeloproliferative neoplasms and regulates the differentiation of planar cell polarity." (PMID 27959900, 2016).
myxoma (1 paper, 2008). A benign soft tissue neoplasm characterized by the presence of spindle and stellate cells, lobulated growth pattern, and myxoid stroma formation. "These confirmations, and new viral–SCRIB interactions we find involving herpes, vaccinia, myxoma, and fibroma viruses (peptides 3–8), suggest that many pathogenic viruses utilize a common mechanism to advantageously target SCRIB-mediated complexes involved in cell polarity and growth control." (PMID 18828675, 2008).
non-small cell lung carcinoma (1 paper, 2021). A group of at least three distinct histological types of lung cancer, including non-small cell squamous cell carcinoma, adenocarcinoma, and large cell carcinoma. "However, in non-small cell lung cancers, SCRIB expression was associated with a favorable prognosis." (PMID 33803371, 2021). "In non-small cell lung cancer cells, SCRIB supported the anti-cancer effects of cisplatin by increasing cisplatin-mediated generation of reactive oxygen species and knock-down of SCRIB induced cisplatin resistance." (PMID 33803371, 2021).
oropharyngeal cancer (1 paper, 2021). Carcinoma, predominantly squamous cell, arising from the epithelial cells of the oropharynx. "This is the first study to analyze the cause-and-effect relationship of DLG1 and SCRIB protein expression levels in a panel of HPV-negative and HPV-positive histologic oropharyngeal cancer samples." (PMID 34503271, 2021).
pancreatic cancer (1 paper, 2025). "The loss of SCRIB drives the progression of invasive pancreatic cancer through both cell‐autonomous and non‐cell‐autonomous mechanisms, correlating with worse patient outcomes." (PMID 40952239, 2025). "SCRIB, a regulator of cell polarity, is often lost or mislocalised in pancreatic tumors, contributing to the transition from an epithelial to a more invasive mesenchymal phenotype." (PMID 40952239, 2025).
scleroderma (1 paper, 2022). Scleroderma is a rare autoimmune connective tissue disorder characterized by abnormal hardening of the skin and, sometimes, other organs. "However, mesenchymal–epithelial transition (MET) associated proteins such as SCRIB, DSP, TJP1, CDH1, DLG1, and TJP2 were downregulated in scleroderma skin, indicating the high severity of skin fibrosis in mice with scleroderma." (PMID 35315234, 2022).
tumor (54 papers, 2004 to 2025). "SCRIB (a scaffold protein found at epithelial adherens junctions and neuronal presynaptic compartments) can act as a tumor suppressor gene and has been shown to be mutated in severe neural tube defects (see OMIM entry 607733)." (PMID 33842847, 2021). "Like DLG1, SCRIB is a key player in cell polarity regulation and is a tumor suppressor, since loss of SCRIB leads to cancerous cellular overgrowth." (PMID 34503271, 2021). "In several studies, the SCRIB gene, which encodes the Scribble protein, is even considered to be a regulator of tumour development and metastasis due to its role in tumour-related mechanisms." (PMID 33937255, 2021). "The tumor-suppressive role of SCRIB is also supported by a report that the loss of SCRIB causes loosening of the cell to cell contact and leading epithelial-to-mesenchymal transition (EMT)." (PMID 33803371, 2021). "For example, ZDHHC7‐mediated palmitoylation of the polarity protein Scribble (SCRIB) is essential for its membrane localisation and tumour‐suppressive function; loss of this modification mislocalises SCRIB, leading to Hippo pathway inhibition and YAP activation." (PMID 40903842, 2025). "SCRIB, encoding the Scribble protein, localizes to cell–cell junctions and mediates the establishment of epithelial cell polarity, was considered as a regulator of tumor development and metastasis." (PMID 37189064, 2023). "We also observed delocalization, suggesting that some post-translational mutations, such as S-palmitoylation, could be involved in this process, resulting in a disruption of cell polarity and loss of SCRIB’s tumor suppressive activities." (PMID 34503271, 2021). "Therefore, as a component of polarity protein, SCRIB has been suggested as a tumor suppressor, and loss of SCRIB induced tumorigenesis in MYC-induced transformed epithelial cells." (PMID 33803371, 2021). "The loss of SCRIB in malignant tumors suggest that it has potential to be a tumor suppressor." (PMID 32564009, 2020). "Consistently, with the potential tumor suppressor role of SCRIB, we found that methylation levels of cg00110724 (SCRIB gene) were higher in the high-risk group than in the low-risk group, suggesting that methylation of SCRIB gene would lead to the loss of tumor suppression and promote CRC." (PMID 33294438, 2020). "Finally, discovered interactors for MAGI1 and SCRIB were analysed with regard to new biological functions that can be linked to MAGI1 and SCRIB and that might be perturbed in tumours induced by oncoviruses or other factors." (PMID 22069443, 2011). "If NOS1AP supports the tumor suppressor function of SCRIB, depletion of NOS1AP in MCF7 KANK1-KO cells should foil the effect of KANK1 on SCRIB-mediated TAZ stability regulation." (PMID 39613731, 2024). "Induced by estrogen signaling in a MYC-dependent manner, cell polarity proteins Scribble (SCRIB) has tumor-promoting function and mediates tumor cell proliferation and endocrine resistance to tamoxifen in ER-positive breast cancer cells." (PMID 38705513, 2024). "Because of the deregulation of SCRIB in human cancers, SCRIB has been suggested to be a tumor suppressor." (PMID 35885485, 2022). "SCRIB gene is closely related to tumors and is considered to be a key factor of tumor development and metastasis." (PMID 36246600, 2022). "Here we show an unexpected role for the cell polarity protein SCRIB as a tumor-promoter and a regulator of endocrine resistance in ER-positive breast cancer cells." (PMID 35501367, 2022). "The role of SCRIB as a component of cell junctions suggests that SCRIB acts as a tumor suppressor because structural and functional alteration of cell polarity induces tumorigenesis." (PMID 33803371, 2021). "Knockout of SCRIB inhibited in vivo tumor growth of SKOV3 cells and overexpression of SCRIB promoted tumor growth." (PMID 33803371, 2021).
tumor (continued). "The complex in which scribble planar cell polarity protein (SCRIB) is located is one of the three main polar protein complexes that play an important role in maintaining epithelial polarity and affecting tumour growth." (PMID 33937255, 2021). "SCRIB mislocalization is shown in breast epithelial carcinogenesis and tumor progression." (PMID 40057606, 2025). "In search for a mechanistic explanation for the increased tumor growth in KANK1-WTPyMT mice, we discovered several steps of an oncogenic signaling pathway, in which KANK1 undertakes the principal task to impair the tumor suppressive function of the cell polarity protein SCRIB." (PMID 39613731, 2024). "ZDHHC7-mediated SCRIB palmitoylation enhances tumor suppressive activity of SCRIB76." (PMID 37828054, 2023). "Considering that DHHC7 is frequently deleted in those and several other cancers, SCRIB palmitoylation and its PM localization could be crucial for SCRIB tumour-suppressive functions." (PMID 35159178, 2022). "Whether these effects on epithelial architecture modulate EGFR-RAS-ERK activation (perhaps through altering SCRIB/DLG1 function) or affect other signaling pathways to contribute to the tumor suppressor function of Tsp29Fb/TSPAN6 needs to be examined." (PMID 35184157, 2022). "Hence a direct relationship between tumor suppression and SCRIB or LLGL2 proteins is controversial in mammals." (PMID 35501367, 2022). "In the liver and breast, the deregulation of SCRIB promoted tumor formation." (PMID 35885485, 2022). "We have discussed in our previous works that the trend of SCRIB expression in different tumours may be different, even opposite." (PMID 33937255, 2021). "Therefore, based on the role of SCRIB as a component of tight junctions, the maintenance of SCRIB is expected as a tumor suppressor or suppressor of EMT." (PMID 33803371, 2021). "However, considering that the function of SCRIB in different, even opposite, in different tumours, it cannot be generally considered to be a cancer-promoting or cancer-suppressing gene." (PMID 33937255, 2021). "Furthermore, overexpression of SCRIB significantly increased in vivo growth of SKOV3 cells, and knockout of SCRIB significantly decreased in vivo tumor growth compared with controls." (PMID 33803371, 2021). "SCRIB affects tumor development by negatively modulating the Wnt/β-catenin signaling pathway." (PMID 34642262, 2021). "Tumour growth was markably suppressed by the knockdown of SCRIB as shown by lower final tumour volumes and weights than those of the control tumours, and overexpression of SCRIB promoted tumour growth." (PMID 33937255, 2021). "FAM83H-mediated in vivo tumor growth was attenuated with knock-down of SCRIB." (PMID 32564009, 2020). "SCRIB has been reported to be frequently amplified in human cancers and to be incorrectly localized at cell-to-cell junctions, suggesting that its mis-localization may impair its tumor suppressor activity." (PMID 35637973, 2022). "Therefore, the role of SCRIB in tumorigenesis and cancer progression might be different according to the type of tumor and stage of progression of cancer, and further study is needed." (PMID 33803371, 2021). "However, there are conflicting reports that SCRIB acts as a tumor suppressor." (PMID 33803371, 2021). "The KANK1-induced disruption of the SCRIB/NOS1AP complex curbs TAZ inhibition, resulting in increased mouse tumor cell growth in vivo, in tumoroids and in xenografted human cancer cells." (PMID 39613731, 2024). "In conclusion, we verified that SCRIB is highly expressed in CRC and participates in tumour progression through in vivo and in vitro experiments." (PMID 33937255, 2021). "The in vivo tumor growth of the cells that were induced to overexpress FAM83H and have a knock-down of SCRIB was intermediate to those of the control and the FAM83H-overexpressing groups." (PMID 32564009, 2020).
tumor (continued). "Notably, CP proteins SCRIB and DLG1 are demonstrated to regulate the antigen presentation in DC, indicating that CP of cancer cells can modulate the polarized localization of tumor antigens to avoid recognition by DC or macrophages." (PMID 40057606, 2025). "It is worth exploring whether CP components like SCRIB and DLG1 affect the localization and function of major histocompatibility complex (MHC) molecules and other APMs in tumor cells." (PMID 40057606, 2025). "In addition to SCRIB there are several noteworthy hits in the AFDN BioID dataset, many of which are tumour suppressors." (PMID 35931706, 2022). "In addition, some point mutations in SCRIB, like P305L in the leucine rich repeat (LRR) region, were reported to cause its relocation from the membrane to the cytoplasm in organotypic 3D MCF10A cultures, which could also be responsible for the phenotype observed in the tumor samples." (PMID 34503271, 2021). "Our new analysis showed that the mRNA level of SCRIB in tumour tissues was significantly increased compared to that in normal colorectal tissues (P = 2.51×10−20)." (PMID 33937255, 2021). "The qRT-PCR and western blot results showed that SCRIB substantially upregulated in tumours tissues compared with the adjacent nontumorous tissues at both the mRNA and protein levels." (PMID 33937255, 2021). "Tumor suppressors DLG1 and SCRIB are two of the principal PDZ domain-containing E6 targets." (PMID 34503271, 2021). "Interestingly, MET treatment increased the expression of SCRIB in the two drug‐resistant cells (LCC2 and MCF/TAX) and in mouse tumours, but only had a weak effect in drug‐sensitive cells (MCF7)." (PMID 32281270, 2020). "Interestingly, the N-terminus of SCRIB is activated in aggressive BC, with the proline-rich C-terminus lost, and SCRIB is favorably localized to the cellular protrusions in metastatic cells; blocking SCRIB inhibits the FRP and tumor metastasis." (PMID 40057606, 2025). "Interestingly, SCRIB was also relocated from cell–cell contacts to the cytoplasm in the tumor samples in comparison with normal tissue, regardless of HPV16 status, but in addition there was an obvious reduction in SCRIB expression in higher grade tumors." (PMID 34503271, 2021).
cancer (37 papers, 2004 to 2024). A tumor composed of atypical neoplastic, often pleomorphic cells that invade other tissues. "FAM83H is involved in cancer progression in association with various oncogenic molecules, including SCRIB." (PMID 35885485, 2022). "As expected, in the majority of HPV-positive OPSCCs, we observed a complete loss of SCRIB protein; in a few samples SCRIB was detected, but at low levels and exclusively in the cytoplasm of cancer cells." (PMID 34503271, 2021). "When SCRIB was overexpressed, SCRIB moved to the cytoplasm, and that was associated with cancer development." (PMID 33803371, 2021). "In addition to the molecular association of FAM83H and SCRIB in human cancers, FAM83H forms a more extensive molecular network in the progression of human cancers." (PMID 35885485, 2022). "Therefore, it is suggested that FAM83H is involved in the progression of human cancers by forming a complex network with the molecules associated with cancer progression and SCRIB in CRCs." (PMID 35885485, 2022). "In this respect, the loss of SCRIB from the cytoplasmic membrane and its aberrant translocation to the cytoplasm and/or nucleus might serve in the development and progression of cancers." (PMID 33803371, 2021). "Thus, the prognostic significance of nuclear localization of SCRIB might be related to the association between SCRIB and nuclear proteins involved in cancer progression, such as snail and β-catenin." (PMID 33803371, 2021). "The information about SCRIB is further confounded by its diverse roles, where it is downregulated in some cancers and upregulated in others." (PMID 38920638, 2024). "SCRIB is overexpressed and mislocated in human cancers, being involved in the regulation of Hippo pathway in BC cells." (PMID 39275004, 2024). "In contrast, luminal cancers show less consistent up-regulation of SCRIB and VANGL2 mRNAs and rare up-regulation of SMURF2 or WNT11." (PMID 36675340, 2023). "Different sub-types show different patterns of mRNA expressions in these PCP players, with most basal cancers displaying up-regulation of SCRIB and VANGL2 mRNAs in both cases where they are amplified and non-amplified for the respective genes." (PMID 36675340, 2023). "A co-expression pattern of nuclear FAM83H and cytoplasmic SCRIB predicted shorter cancer-specific survival (p < 0.001) and relapse-free survival (p = 0.032) in multivariate analysis." (PMID 35885485, 2022). "We also report a function for the SCRIB/LLGL polarity complex in cancer cells as a regulator of membrane trafficking of the SLC7A5/SLC3A2 amino acid transporter complex." (PMID 35501367, 2022). "In our human CRC tissue, the expressions of FAM83H and SCRIB were primarily seen in the cytoplasm and nuclei of the cancer cells." (PMID 35885485, 2022). "The nuclear expressions of FAM83H and SCRIB and the cytoplasmic expression of SCRIB were independent indicators of shorter cancer-specific survival in multivariate analysis." (PMID 35885485, 2022). "It has been reported that Vimentin upregulation during EMT enhances tumorigenesis via targeting 14–3-3-mediated cell cycle control, and increases the migratory and invasive capacity of cancer cells by stabilizing scaffold protein SCRIB." (PMID 33530981, 2021). "SCRIB was predominantly localized in the cytoplasm of cancer cells, while we detected SCRIB both in the cytoplasm and at cell–cell contacts in only one sample." (PMID 34503271, 2021). "The cut-off points of immunohistochemical staining scores for the nuclear expression of SCRIB (nSCRIB) and cytoplasmic expression of SCRIB (cSCRIB) were determined with ROC analysis to predict the death of cancer patients." (PMID 33803371, 2021). "Alteration of SCRIB localization at the membrane often mimics SCRIB loss-of-function phenotype and SCRIB aberrant accumulation in the cytosol strongly correlates with poor survival in human cancers." (PMID 25664942, 2015).